FCMR (Fc mu receptor)
Description:
High-affinity Fc receptor for immunoglobulin M (IgM), both secreted and membrane-bound IgM. Primarily regulates IgM transport and homeostasis. In lymphoid cells, enables exocytosis of membrane-bound IgM on the plasma membrane as well as endocytosis of IgM-antigen complexes toward lysosomes for degradation. In mucosal epithelium, mediates retrotranscytosis of antigen-IgM complexes across mucosal M cells toward antigen-presenting cells in mucosal lymphoid tissues. Triggers costimulatory signaling and mediates most of IgM effector functions involved in B cell development and primary immune response to infection. Likely limits tonic IgM BCR signaling to self-antigens for proper negative selection of autoreactive B cells in the bone marrow and for the maintenance of regulatory B cell pool in peripheral lymphoid organs. Mediates antibody responses to T cell-dependent and T cell-independent antigens and promotes induction of an efficient neutralizing IgG response. Engages in cross-talk with antigen-receptor signaling via the non-canonical NF-kappa-B, MAP kinases and calcium signaling pathways.
Synonyms: IgM FcR; FAIM3; TOSO; FcmuR
Tractability: Antibody: UniProt places it where antibodies can reach, with high confidence; its Gene Ontology location is reachable by antibodies, with high confidence; UniProt predicts a signal peptide or a membrane-spanning region.
Gene: Protein-coding gene on chromosome 1 (206,903,317 to 206,923,247, reverse strand). Ensembl gene ENSG00000162894.
Subcellular location: Cell membrane; Early endosome membrane; Golgi apparatus, trans- Golgi network membrane; Lysosome membrane; Secreted (Isoform 3)
Subcellular location (Human Protein Atlas): Nucleoplasm; Plasma membrane; Centrosome; Golgi apparatus; Predicted to be secreted
Gene Ontology:
Molecular function: high-affinity IgM receptor activity; polymeric immunoglobulin binding; protein binding; IgM binding; transmembrane signaling receptor activity
Biological process: Fc receptor-mediated immune complex endocytosis; cellular defense response; humoral immune response mediated by circulating immunoglobulin; immunoglobulin transcytosis in epithelial cells; negative regulation of apoptotic process; regulation of B cell receptor signaling pathway; signal transduction; Fc receptor signaling pathway
Cellular component: early endosome membrane; extracellular region; Golgi apparatus; lysosomal membrane; plasma membrane; trans-Golgi network membrane
Genetic constraint (gnomAD): Loss-of-function variants: 30 observed, 33.14 expected, observed/expected ratio (o/e) 0.91, 90% interval 0.68 to 1.23. The upper end of that interval is the gene's LOEUF score, 1.23, which puts it in group 5 of 6, group 1 being the genes least tolerant of losing a copy. Missense variants: 482 observed, 459.95 expected, observed/expected ratio (o/e) 1.05, 90% interval 0.97 to 1.13. Synonymous variants: 203 observed, 185.16 expected, observed/expected ratio (o/e) 1.1, 90% interval 0.98 to 1.23.
Homologues: Orthologues: chimpanzee FCMR (99% identical), macaque FCMR (91% identical), dog FCMR (67% identical), pig FCMR (67% identical), mouse Fcmr (59% identical), rat Fcmr (57% identical), guinea pig FCMR (55% identical). Paralogues in human: PIGR (17% identical), CD300A (15% identical), CD300LG (15% identical), FCAMR (15% identical), CD300C (13% identical), CD300LB (13% identical), CD300E (13% identical), CD300LF (13% identical), TREML1 (13% identical), CD300H (13% identical), CD300LD (13% identical), TREM2 (10% identical), and 1 more.
Diseases named in the same sentence as FCMR in open-access papers:
FCMR is named in the same sentence as 17 diseases in open-access papers, as found by Europe PMC text mining. Sharing a sentence is not in itself a finding about the gene and the disease. The quoted sentences say what the papers report.
Autoimmunity (2 papers, 2016 to 2019). The occurrence of an immune reaction against the organism's own cells or tissues. "In addition to this newly described role in anti-tumor immunity, FCMR is also clearly critical for autoimmunity, and for immune responses to bacteria and virus." (PMID 31213601, 2019). "Thus, sIgM and FCMR may negatively regulate autoimmunity through the sIgM–FCMR pathway not withstanding that sIgM may also modulate autoimmune responses through FCMR-independent mechanisms, such as complement fixation, immune complex uptake, and antigen presentation." (PMID 27014278, 2016).
B-cell lymphoma (1 paper, 2025). "Strikingly, all the top proteins associated with B-cell lymphoma development (sCD23, FCMR, FCRL1, FCRL3, SELL, SEMA7A and SEMA4A) were most strongly associated with CLL development, suggesting CLL was a major driver of the top protein associations observed in the grouped analysis." (PMID 40894013, 2025). "Top proteins specifically associated with non-germinal center-derived B-cell lymphoma included FCMR, SPOCK2, IGSF3 and SEMA4A." (PMID 40894013, 2025).
cervical cancer (1 paper, 2024). A primary or metastatic malignant neoplasm involving the cervix. "For instance, in cervical cancer, TGIF2 downregulates FCMR by binding directly to its promoter, thereby promoting cervical cancer metastasis." (PMID 38629068, 2024).
lymphoma (1 paper, 2020). A malignant (clonal) proliferation of B- lymphocytes or T- lymphocytes which involves the lymph nodes, bone marrow and/or extranodal sites. "ABC-DLBCL cells predominantly express IgM isotype antibodies, suggesting that autocrine FCMR signaling may contribute to tumorigenesis in lymphomas with ETS1-driven FCMR upregulation." (PMID 32679859, 2020).
tumor (3 papers, 2019 to 2025). "It has been found that Fc fragment of IgM receptor (FcmR) expressed by mononuclear macrophages in myeloma promotes tumor growth." (PMID 40535807, 2025). "Therefore, blocking FcmR through targeted therapy can inhibit tumor growth and invasion." (PMID 40535807, 2025). "FCMR expression in cell types that have important roles in modulating TME maintenance and anti-tumor immunity, such as monocytes, activated MΦ, and DCs, suggests a potential function for FCMR in myeloid cells function during cancer progression." (PMID 31213601, 2019).
infection (1 paper, 2016). The state of being infected such as from the introduction of a foreign agent such as serum, vaccine, antigenic substance or organism. "While sIgM has long been postulated to play an important role as first line in defense against infectious agents, there are also indications that FCMR may play a role during inflammatory responses to infection." (PMID 27014278, 2016).
FCMR also shares sentences with these, for which no sentence is quoted: breast carcinoma (2 papers); cancer (1); chronic lymphocytic leukemia (1); experimental autoimmune encephalomyelitis (1); Immunodeficiency (1); leukaemias (1); lupus (1); meningioma (1); mouth ulcers (1); myocardial ischemia (1); pancreatic ductal adenocarcinoma (1).